ZNF524 (zinc finger protein 524)
Description:
May be involved in transcriptional regulation.
Synonyms: MGC23143
Tractability: Small molecule: a structure with a bound ligand is known.
Gene: Protein-coding gene on chromosome 19 (55,599,714 to 55,603,138, forward strand). Ensembl gene ENSG00000171443.
Subcellular location: Nucleus
Subcellular location (Human Protein Atlas): Nucleoplasm
Gene Ontology:
Molecular function: protein binding; sequence-specific double-stranded DNA binding; DNA-binding transcription factor activity; RNA polymerase II cis-regulatory region sequence-specific DNA binding
Biological process: telomere organization; regulation of transcription by RNA polymerase II
Cellular component: chromosome, telomeric region; nucleus
Genetic constraint (gnomAD): Loss-of-function variants: 1 observed, 0.54 expected, observed/expected ratio (o/e) 1.84, 90% interval 0.34 to 1.92. That is too few expected variants to judge how well the gene tolerates losing a copy. Missense variants: 114 observed, 95.7 expected, observed/expected ratio (o/e) 1.19, 90% interval 1.02 to 1.39. Synonymous variants: 52 observed, 41.95 expected, observed/expected ratio (o/e) 1.24, 90% interval 0.99 to 1.56.
Homologues: Orthologues: chimpanzee ZNF524 (99% identical), macaque ZNF524 (97% identical), dog ZNF524 (92% identical), pig ZNF524 (84% identical), mouse Zfp524 (80% identical), guinea pig ZNF524 (80% identical), rat Zfp524 (80% identical), tropical clawed frog znf524 (43% identical). Paralogues in human: ZNF581 (36% identical), ZBTB49 (25% identical), ZNF580 (25% identical), FEZF1 (23% identical), FEZF2 (21% identical), ZBTB7B (21% identical), ZNF683 (20% identical), PRDM13 (18% identical), BCL6 (18% identical), BCL6B (18% identical), ZNF280D (17% identical), ZBTB21 (17% identical), and 16 more.
Diseases named in the same sentence as ZNF524 in open-access papers:
ZNF524 is named in the same sentence as 1 disease in open-access papers, as found by Europe PMC text mining. Sharing a sentence is not in itself a finding about the gene and the disease.
ZNF524 shares sentences with these, for which no sentence is quoted: breast carcinoma (1 paper).